MMP9 (matrix metallopeptidase 9)
Diseases named in the same sentence as MMP9 in open-access papers (continued):
Sharing a sentence is not in itself a finding about the gene and the disease.
tongue cancer (13 papers, 2012 to 2025). A malignant neoplasm affecting the tongue. "It was also demonstrated that emodin inhibited protein levels and activities of matrix metalloproteinase-2 (MMP-2), the gene expression of MMP-9, and the migration and invasion of human tongue cancer SCC-4 cells." (PMID 34073059, 2021). "The molecular targeting of MMP-9 mRNA expression by emodin can be a beneficial strategy for chemoprevention and/or chemotherapeutics of tongue cancers." (PMID 34073059, 2021). "Gyps suppressed the invasion and migration of SCC4 human tongue cancer cells in a dose- and time-dependent manner by downregulating nuclear factor kappa B (NF-κB) and matrix metalloproteinase-9 (MMP-9)." (PMID 27708693, 2016). "As high as 80% (40/50; P = 0.0001) of tongue cancer cases showed strong expression of MMP-9, 68% (34/50; p = 0.06) for Bcl-2 and 78% (39/50; P = 0.0001) for cyclin D1 genes." (PMID 26581505, 2015). "In order to examine the effect of Fra-2 silencing on AP-1 target genes associated with aggressive tumorigenesis, we checked the expression of Bcl-2, MMP-9 and cyclin D1 in siRNA treated tongue cancer cell lines." (PMID 26581505, 2015). "We have also examined the role of AP-1 downstream target genes Bcl-2, MMP-9 and Cyclin D1 in tongue cancer." (PMID 26581505, 2015). "We observed significantly a higher expression of MMP-9, cyclin D1 and Bcl-2 genes in majority of tongue cancer cases and cancer cell lines particularly in HPV−ve cases that show aggressive tumor and worst prognosis." (PMID 26581505, 2015). "In other words, expression of MMP-9 protein was significantly increased in tongue cancer cells with strong proliferative ability, although such correlation was not significant for MMP-2." (PMID 23107277, 2012). "In addition to the occurrence of autophagy, we also found that the tumorigenesis-related factor (MMP-9 and RhoC genes) expression was decreased in vitro and in 4NQO-induced mouse tongue cancers in this study." (PMID 36247874, 2022). "In addition, compared with the 4NQO+captisol group, MK2206 2HCl also significantly reduced MMP-9 and RhoC expression in 4NQO-induced mouse tongue cancers in the 4NQO+MK2206 2HCL group via IHC staining." (PMID 36247874, 2022). "Interestingly, oral keratinocytes and SAS tongue cancer cells express MMP-9, and ANE stimulates MMP-9 but suppresses TIMP-1 and TIMP-2 secretion via differential signaling pathways." (PMID 33143101, 2020). "Those hub genes involved in pathways of cancer are Bcl2, EGFR, ESR1, MMP9, PPARG, and MMP2 and those involved in PI3K-Akt signaling pathways are Bcl2, EGFR, CDK2, and MCL1 these genes are considered therapeutic targets for tongue cancer." (PMID 39863836, 2025). "To further detect the mechanism of the chemopreventive effect of MK2206 2HCl, we also detected MMP-9 and RhoC (key regulators of tumorigenesis) expression in OSCC cells and 4NQO-induced mouse tongue cancers through RT-PCR, western blotting, and IHC." (PMID 36247874, 2022). "MMP-9 and MMP-13 were found to be significantly upregulated in tongue cancer, further confirmed this function." (PMID 32236620, 2020). "In tongue cancer the CCL5/CCR5 axis stimulated increased cell migration and the expression of MMP9 has been proposed to be mediated through NF-kappaB signaling pathways." (PMID 24204919, 2013). "The peptides CTTHWGFTLC and GRENYHGCTTHWGHTLC also inhibit gelatinase B/MMP-9 catalytic activity but not gelatinase B/MMP-9 activation and inhibit primary HSC-3 tongue carcinoma growth but not tumor spread in a mouse model." (PMID 24473089, 2014).
amyloid (12 papers, 2010 to 2025). "In addition, MMP2 and MMP9 levels have been shown to be associated with cerebral hemorrhage resulting from vascular amyloid deposition (that is, CAA)." (PMID 24991237, 2014). "ApoE-driven AD pathologies differ from pure amyloid pathologies and our prior work indicates apoE can regulate MMP9 disposition in the brain, and the apoE4 isoform in particular is associated with elevated MMP9 levels and activity." (PMID 34034683, 2021). "Incubation of fresh slices for 2 weeks with 1–0.1–0.01 μg/ml of NEP, insulysin, MMP-2, or MMP-9 showed that NEP, insulysin, and MMP-9 markedly degraded beta-amyloid plaques but only at the highest concentration." (PMID 25914642, 2015). "Through the course of analyzing the effect of MMP9-expressing NSCs on amyloid plaque burden in our two models of Alzheimer-type amyloidosis, we found robust endogenous metalloproteinase activity specifically around Aβ plaques." (PMID 22496779, 2012). "In this test case, we investigated the potential efficacy of MMP9 in promoting the clearance of amyloid deposits." (PMID 22496779, 2012). "For reasons delineated above, secreted MMP9 is an excellent candidate biologic for enhancing the clearance of amyloid deposits." (PMID 22496779, 2012). "In AD, the expressions of MMP-3 and MMP-9 are elevated in the brain and are located around neurofibrillary tangles and amyloid plaques." (PMID 20576109, 2010). "Resveratrol may maintain the integrity of the BBB via reduction of MMP9 and induce adaptive immune responses that may promote brain resilience to amyloid deposition." (PMID 28086917, 2017). "One potentially interesting observation was that the area near the engrafted NSCs, whether expressing MMP9 and GFP or GFP alone, showed modest reductions in amyloid plaque numbers in the APPswe/PS1dE9 model and in tetAPPsi mice." (PMID 22496779, 2012). "Additionally, apoE4 accelerates the degradation of the BBB through activation of the cyclophilin A-matrix metalloproteinase-9 (MMP9) pathway in pericytes, whereas suppression of this pathway improves BBB integrity and prevent apoE4-mediated behavioral deficits in amyloid mouse models." (PMID 36348357, 2022).
Arrhythmia (12 papers, 2013 to 2025). Any cardiac rhythm other than the normal sinus rhythm. "CTA, MMP-9 and PAF are excellent for diagnosing stenosis after ACS, and shorter breath-hold time and arrhythmia are all independent risk factors for poor CTA image quality." (PMID 40821655, 2025). "In this multi-ethnic study cohort, we found that RANTES is associated with sex, EMMPRIN is associated with a history of arrhythmia and LDL levels, MMP-2 with age, and MMP-9 with ethnicity and hs-CRP levels." (PMID 36555898, 2022). "The serum MMP-9 level was higher in patients with recurrence, and it was identified as an independent predictor of arrhythmia relapse after catheter ablation in patients with persistent AF." (PMID 27276393, 2016). "In this study, we observed the relationship between the serum MMP-9 level and arrhythmia recurrence after catheter ablation for persistent AF." (PMID 27276393, 2016). "In the present study, we prospectively explored the predictive value of the MMP-9 level for recurrent arrhythmia after catheter ablation." (PMID 27276393, 2016). "However, the involvement of other genes, including CXCL8, FOS, CCL2, and MMP9, in aconitine-induced arrhythmias warrants further research." (PMID 35915792, 2022). "MG could attenuate VCAM-1, ICAM-1, MCP-1, and MMP9, inhibit the proliferation of smooth muscle cells and fibroblasts, and obtain arrhythmia from I/R injury to show cardiovascular protection." (PMID 33815113, 2021). "However, irregular calcium transients and sparks mimicking clinical arrhythmia were inhibited by a specific MMP-9 inhibitor in hiPSC-CMs, which satisfied our desire to validate the functional impact and pathogenesis of MMP-9 in human cardiomyocytes." (PMID 27966586, 2016). "Thus, the attenuation of MMP-9 gene expression after ExT may have contributed to the improvement of arrhythmias in mice with CCC, as observed in the present study." (PMID 40356773, 2025). "The present study shows a significant increase in concentration of MMP-9 in the group of patients with POAF, and this indicator, according to multivariate regression analysis, turned out to be an independent predictor of arrhythmia." (PMID 37895417, 2023). "However, patients with recurrent arrhythmia had a longer history of AF, larger LAD and higher serum MMP-9 levels compared with the non-recurrent group." (PMID 27276393, 2016).
autism (12 papers, 2015 to 2025). Persistent deficits in social interaction and communication and interaction as well as a markedly restricted repertoire of activity and interest as well as repetitive patterns of behavior. "Another hypothesis is related to continuous disturbances in MMP-9 gene transcription by unknown specific factors, which may be supported by the result of mutation in FMR1gene (leading to autism), in which the FMpR protein, natural of MMP-9 translation inhibitor, is missing." (PMID 24633733, 2015). "The down-regulation of MMP-9 in the brain of PPA-induced autism-like rats is unexpected because elevated brain MMP-9 levels after PPA exposure amplify neuroinflammation by activating TNF-α and other pro-inflammatory markers and promote autistic-like features." (PMID 35334937, 2022). "Finally, we investigated a possible causal link between MMP-9 activation and BDNF upregulation, increased brain size, and autism phenotypes in ZnT3 null mice." (PMID 27352957, 2016). "Regulation of transcript expression by ELAVL2 has been shown to be critical for neuronal function and clinically relevant to autism, and ELAV1/HUR and ELAV2/HUB are critical for the occurrence of MMP-9 mRNA stabilization upon neuronal activation." (PMID 36005139, 2022). "Our study showed that PPA treatment significantly decreased the expression of MMP-9, BDNF, ICAM, Synapsin I, PSD-93, and PSD-95 but elevated GFAP in the brain of PPA-induced PPA-induced autism-like rats." (PMID 35334937, 2022).
Infertility (12 papers, 2014 to 2025). "We found a positive association of MMP-9 with IL-17 suggesting that inflammation can increase MMP-9 levels in subjects with infertility." (PMID 33997592, 2021). "The percent of immotile sperm in infertile men withthe CC and CT genotypes of C-1562T MMP-9 gene polymorphism significantly differed compared with that of subjectswith the TT genotype." (PMID 29043698, 2018). "MMP-9 was associated with NO and duration of infertility in PCOS." (PMID 32923927, 2020). "Therefore, the aim of this study was to determine the prevalence of C-1562T MMP-9 (rs3918242) gene polymorphism in fertile and infertile men." (PMID 29043698, 2018). "In this study, we divided the infertile men into asthenozoospermic and terato-asthenozoospermic groups according to their semen profiles, and determined the frequencies of the genotype C-1562T MMP-9 gene polymorphisms." (PMID 29043698, 2018). "NGAL and MMP-9 levels in venous blood samples and the MMP-9/NGAL ratios of the unexplained infertility and endometrioma groups and the preoperative and postoperative results of the endometrioma group were compared." (PMID 40810077, 2025). "The results consistently showed that serum MMP-9 levels were higher in EMT patients than in infertile patients with hydrosalpinx, further supporting the potential role of MMP-9 in the pathological process of EMT." (PMID 39544239, 2024). "Table II presents the association of IL-17 and MMP-9 with semen analysis parameters, PSS, age and the duration of infertility in infertile cases." (PMID 33997592, 2021). "Table III shows the effect of psychological stress on semen parameters, IL-17 and MMP-9 in infertility cases." (PMID 33997592, 2021). "In infertile cases, MMP-9 and IL-17 were significantly increased when compared with controls (p = 0.046, p = 0.041 respectively)." (PMID 33997592, 2021). "In the present study MMP-9 was significantly increased in infertility cases when compared with controls (p = 0.046)." (PMID 33997592, 2021). "In the present study, IL-17 and MMP-9 were significantly elevated in infertility cases compared to controls." (PMID 33997592, 2021). "In the present study, MMP-9 levels negatively correlated with NO levels and positively correlated with the duration of infertility in PCOS subjects." (PMID 32923927, 2020). "MMP-9 levels positively correlated with the duration of infertility (r = 0.253, p = 0.047) and negatively correlated with NO levels (r = - 0.259, p = 0.042)." (PMID 32923927, 2020). "In our study, we observed that MMP-9 levels were higher in infertile women with PCOS having a BMI > 30 kg/m2 compared to those with BMI between 25 and 28 kg/m2." (PMID 32923927, 2020). "MMP-9 levels are increased in obese PCOS women and it is associated with NO levels and the duration of infertility." (PMID 32923927, 2020). "MMP-9 was positively correlated with the duration of infertility (r = 0.253, p = 0.047) and negatively correlated with NO (r = -0.259, p = 0.042)." (PMID 32923927, 2020). "We also found that the frequency of individuals with both positive MMP-9 T allele and MMP-2 A allele was significantly different in the fertile group compare with the infertile individuals." (PMID 29043698, 2018). "The frequency of CC/GA-combined genotypes of C-1562T MMP-9 and G-1575A MMP-2gene polymorphisms significantly differed in fertile and infertile men (P=0.031)." (PMID 29043698, 2018). "The aim of this study is to determine the prevalence of C-1562T MMP-9 (rs3918242) gene polymorphismin fertile and infertile men." (PMID 29043698, 2018). "The synergistic analysis of genotypes of C-1562T MMP-9 and G-1575A MMP-2 gene polymorphisms showed that the frequency CC/GA-combined genotype was significantly different between fertile and infertile men." (PMID 29043698, 2018). "In this study we determine the prevalence of the C-1562T MMP-9 gene polymorphism and its associationwith the G-1575A of MMP-2 gene polymorphism infertile and infertile men." (PMID 29043698, 2018).
Infertility (continued). "Further studies are needed to investigate whether a reduction in inflammation and stress could reduce MMP-9 and normalizes the semen parameters in men with infertility." (PMID 33997592, 2021). "IL-17 and MMP-9 were significantly increased and sperm count, motility and morphology were significantly decreasedin cases indicating the presence of inflammation and abnormal semen parameters in men with infertility." (PMID 33997592, 2021). "The semen profiles of infertile subjects with referenceto the MMP-9 genotypes are described." (PMID 29043698, 2018). "Our results indicated that the variant genotype -1562 CC in the MMP9 gene did not have a significant association with an increased risk of infertility [adjusted OR=1.34, 95% confidence interval (CI): 0.88-2.02 and OR=1.44, 95% CI: 0.52-3.98]." (PMID 29043698, 2018). "In addition, the association between C-1562T of MMP-9 and G-1575A of MMP-2 gene polymorphism in fertile and infertile men was determined." (PMID 29043698, 2018). "The study indicated that in theC-1562T MMP-9 gene polymorphism, the frequenciesof CT and TT genotypes did not significantly differ infertile and infertile men." (PMID 29043698, 2018). "On the other hand, synergistic analysis of alleles G-1575A MMP-2 and C-1562T MMP-9 gene polymorphisms showed that the frequency of individuals with negative MMP-9 T allele and positive MMP-2 A allele between fertile and infertile men was significantly different." (PMID 29043698, 2018). "In this study, we aimed to investigate whether serum NGAL, MMP-9 and the MMP-9/NGAL ratio, which are inflammatory markers used for the diagnosis and follow-up of some diseases, can be used as diagnostic and follow-up markers for the diagnosis of endometriomas in infertile patients." (PMID 40810077, 2025). "MMP-9 was positively correlated with PSS and IL-17 in subjects with infertility." (PMID 33997592, 2021). "Moreover, MMP‐9 depletion and MUC1 overexpression may be considered as part of a complicated pathway leading to infertility and to the progression of carcinogenesis." (PMID 28244681, 2017).
laryngeal carcinoma (12 papers, 2013 to 2023). Carcinoma that arises from the laryngeal epithelium. "Studies have found that MMP-9 is highly expressed in HNSCC and identified that MMP-9 expression is associated with lymph node metastasis and poor outcome in laryngeal cancer." (PMID 27793010, 2016). "Extracellular matrix degradation-related proteins, MMP-2 and MMP-9 were highly expressed in laryngeal carcinoma, overexpression of which was related to tumor migration and invasion." (PMID 35953439, 2022). "Other immunohistochemical studies have additionally shown that the primary source of MMP-9 in laryngeal carcinoma that promotes EMT is the inflammatory cells in the tumor stroma." (PMID 36140250, 2022). "Western blotting and IF analyses showed that the ectopic expression of PRMT5 induced EMT with downregulation of E-cadherin and upregulation of N-cadherin, snail, and MMP9 in laryngeal carcinoma cells." (PMID 33060569, 2020). "Our study revealed MMP-9 expression in 34% of laryngeal carcinoma tissues in tumor cells and in 96% of cases in stromal compartment cells." (PMID 31143300, 2019). "The high serum index in patients with laryngeal cancer is a result of the high MMP-9 concentration in that group." (PMID 31143300, 2019). "In laryngeal carcinoma, MMP-9 is mainly produced by stroma and tissues surrounding the tumor, which proves the interactions among cells and prepares the surrounding tissues for the tumor invasion." (PMID 31143300, 2019). "There are only a few studies available where the MMP-9 level in blood was examined in the laryngeal carcinoma patients." (PMID 31143300, 2019). "Weiyi Wang found that dihydroartemisinin could inhibit STAT3 activation, down-regulate MMP-9, and affect the invasion and metastasis of cancer stem cells (CSCs) in laryngeal cancer." (PMID 36941602, 2023). "Moreover, active PI3K/AKT increases MMP-9-mediated EMT in laryngeal cancer cells." (PMID 32961679, 2020). "Therefore, the goal for our study was to evaluate the MMP-9 expression in laryngeal cancer and adjacent normal tissues with the correlation to blood concentrations in order to achieve a better knowledge of the role of MMP-9 and its inhibitor in laryngeal carcinoma." (PMID 31143300, 2019). "Less differentiated laryngeal carcinomas appear with enhanced expression of metalloproteinases such as MMP-2 and MMP-9 and suppressed expression of the tissue inhibitors of metalloproteinases TIMP -1 and -2." (PMID 36140250, 2022). "This study demonstrated for the first time the tissue expression and the concentrations of MMP-9 and TIMP-1 in serum and plasma in patients with laryngeal carcinoma." (PMID 31143300, 2019). "The balance between the level of MMP-9 and TIMP-1 is disrupted in laryngeal carcinoma." (PMID 31143300, 2019). "The aim of this study was to assess the expression of MMP-9 and TIMP-1 in cancerous tissue as well as in serum and plasma concentrations of these proteins in patients with laryngeal cancer and compare the results to the inflammatory reaction in healthy subjects." (PMID 31143300, 2019). "In the relevant literature, we have not found any studies where the MMP-9 concentration in serum or plasma obtained in an isolated laryngeal carcinoma group was measured using immunoenzymatic assays." (PMID 31143300, 2019). "The aim of this study was to assess the expression of MMP-9 and TIMP-1 in cancerous tissue as well as in the serum and plasma concentrations of these proteins in patients with laryngeal cancer and compare the results to the inflammatory reaction in healthy subjects." (PMID 31143300, 2019). "The balance between the level of MMP-9 and TIMP-1 is disrupted in laryngeal cancer." (PMID 31143300, 2019). "Moreover, the authors suggested that miR-744-3p enhances the pro-metastatic ability of laryngeal cancer cells through programmed cell death 4 (PDCD4) and PTEN targeting, leading to the activation of matrix metallopeptidase 9 (MMP-9), which enables cancer cell migration." (PMID 35406495, 2022).